EPCAM (epithelial cell adhesion molecule)
Diseases named in the same sentence as EPCAM in open-access papers (continued):
Sharing a sentence is not in itself a finding about the gene and the disease.
tumor (continued). "Therefore, EpCAM-based enrichment in tumor spread may underestimate the importance of CTC, CTSC, and EMT-positive tumor cells, and pure EpCAM may not be a perfect marker for detecting CTC." (PMID 31767014, 2019). "The presence of CTC exhibiting different phenotypes in the same patient due to tumor heterogeneity induced Terstappen and Co. to conduct in-depth studies on CTC detection through the CellSearch® system, with a focus on discarded ones expressing no or low EpCAM." (PMID 31636732, 2019). "The clinical value of ISET® is predictably related to its capacity to isolate all types of tumor cells including tumor cells in Epithelial to Mesenchymal Transition (EMT), expressing mesenchymal markers such as Vimentin, but not (or barely) expressing epithelial markers (EpCAM or cytokeratin)." (PMID 28060956, 2017). "Hence, although EpCAM over-expression is not a common phenomenon in HCC nodules, it is, based on experimental and clinical data, of foremost relevance for the initiation of metastases and tumor aggressiveness." (PMID 29163804, 2017). "Furthermore, in primary HCC, not only did the level of EpCAM and CD90 expression vary greatly among different individuals, but the cell populations expressing EpCAM and CD90 were distinctively localized without overlap even in a given tumor derived from a single patient." (PMID 24713374, 2014). "In the present study, we aimed to compare the methylation profiles of DNA extracted from an EpCAM-enriched cell fraction and from non-enriched CRC cells (whole tumor DNA) to determine whether such cellular enrichment with tumor cells would increase the sensibility of the results." (PMID 24362576, 2013). "Hcc-3 may have originated from a CD56+/CK19+/EpCAM+ microscopic nodule, and hcc-2 from a S100A4+/CK19−/CD56− microscopic nodule; the majority of the tumour mass (which was negative for CD56 and S100A4 but expressed EpCAM and CK19) generated hcc-1, the most aggressive of the three cell populations." (PMID 21731718, 2011). "ctDNA may also capture the HR status from tumor cell populations without EpCAM expression, which could explain the concordant absence of HRD(ctDNA) and of HRD(CyTOF) in cells from patient #55 when gating via CD45−/panCK+ rather than via the stringent CTC marker combination CD45−/panCK+/EpCAM+." (PMID 40456663, 2025). "EpCAM-based methods, therefore, fail to efficiently capture mesenchymal cells, leading to the selective isolation of CTC phenotypes that may not be representative of most cells being shed from a tumor that have the ability to establish themselves and grow at a distal site." (PMID 36358657, 2022). "In addition to existence of individual aneuploid CTCs and tumor CECs identified in carcinoma patients in this study, surprisingly, some aneuploid neoplastic cells and CTMs in cancer patients were found to have a non-reported, unique phenotype of CD31+/EpCAM+/Vimentin+." (PMID 28852197, 2017). "Moreover, EpCAM is not a CTC-specific marker per se, but rather a marker of all epithelial cells; thus, it is possible that some CTCs enriched in this manner may not be tumor cells but rather benign epithelial cells, thus reducing the specificity of EpCAM-based enrichment." (PMID 28191452, 2017).
cancer (1,983 papers, 1987 to 2026). A tumor composed of atypical neoplastic, often pleomorphic cells that invade other tissues. "Epithelial cell adhesion molecule (EpCAM), a multifunctional cell-surface protein, is implicated in proliferation, migration, and stemness in various cancers." (PMID 41785279, 2026). "A promising and druggable cancer-associated molecular target is the epithelial cell adhesion molecule (EpCAM, also known as CD326)." (PMID 40508045, 2025). "Exosomes contain a variety of transmembrane proteins (e.g., CD63, CD9, CD81) and cancer-associated biomarkers (e.g., EpCAM, EGFR)." (PMID 39943486, 2025). "The spectrum and magnitude of cancer risk among LS families vary depending on which specific MMR or EPCAM gene is mutated." (PMID 41164816, 2025). "One of the promising druggable cancer-associated molecular targets is epithelial cell adhesion molecule (EpCAM, also known as CD326)." (PMID 40445498, 2025). "Although EpCAM-based techniques are usually implicated in the detection of CTCs, many CTCs found in patients with various cancers lack adequate epithelial features due to their epithelial-to-mesenchymal transition (EMT)." (PMID 40647654, 2025). "For instance, elevated expression levels of PD-L1 and epithelial cell adhesion molecule (EpCAM) are commonly associated with various types of cancer." (PMID 39776815, 2025). "Elevated EpCAM expression in cancer is often associated with poor prognosis, as EpCAM has been implicated in chemoresistance and metastasis." (PMID 40792441, 2025). "In light of this association with tumorigenesis, the EpCAM gene has recently been recognized as a potential target for cancer therapy." (PMID 40391083, 2025). "In this study, the PD-L1 level was upregulated by threefold in breast CSCs compared with more differentiated cancer cells, and the expression was associated with EpCAM+/CD44high/CD24low alongside EpCAM+/CD90+CSCs." (PMID 41233805, 2025). "Treg levels correlate with EpCAM+ expression in cancer-derived epithelial cells in ascites and are associated with cancer progression." (PMID 40136652, 2025). "In OSCC, EpCAM expression increases during cancer development and is linked to promoter methylation; however, it does not significantly correlate with the overexpression of DNA methyltransferase-1 in OSCC tumors." (PMID 39996844, 2025). "This makes individuals with EPCAM deletions susceptible to other LS-associated cancers, including ovarian, gastric, small bowel, and urinary tract malignancies." (PMID 40452892, 2025). "EPCAM is a marker for cancer stem cells that are associated with cancer proliferation, adhesion, and differentiation, and it is overexpressed in different types of cancer, including PCa." (PMID 38052461, 2024). "It was shown that an increased count of CTCs expressing EpCAM was linked to reduced overall survival across diverse cancer types." (PMID 39456890, 2024). "The overexpression of epithelial cell adhesion molecule (EpCAM) is a hallmark of various cancers, while it maintains normal expression in healthy cells." (PMID 38919334, 2024). "EpCAM, an antigen associated with cancer, is commonly observed to be upregulated in cancer cells originating from epithelial tissues." (PMID 39492906, 2024).
cancer (continued). "Recent studies have implicated cancer stem cells (CSCs), particularly those expressing epithelial cell adhesion molecule (EpCAM), in HCC progression and resistance." (PMID 38929532, 2024). "In non-cancer diseases, the disturbance in EpCAM expression is also linked to function and phenotype." (PMID 38791091, 2024). "Upon irradiation, MHC-I and PD-L1 increased on leukocytes (CD45.2+) and cancer associated fibroblasts (CD45.2−/EpCAM−/CD90.1+)." (PMID 39009951, 2024). "The combined drug treatment assay demonstrated that a CAF-targeted drug (pirfenidone, PFD) significantly enhanced the sensitivity of LC22 cancer cells to Taxol and caused more apoptotic as well as dead EpCAM+/E-cadherin+ cancer cells." (PMID 38643164, 2024). "WDR43 expression demonstrated better association with the 5 different MMR genes in pan-cancer, except for gene EPCAM in LGG." (PMID 39093744, 2024). "This is a significant gap because CTC heterogeneity, manifested through differential expression of surface proteins like EpCAM, plays a crucial role in drug resistance, treatment response, cancer progression, and the risk of disease relapse." (PMID 38675353, 2024). "EPCAM encodes an antigen related to carcinoma called epithelial cell adhesion molecule, which is expressed in malignant epithelial tumors." (PMID 39071494, 2024). "This work builds upon the insights of our prior study that examined the effects of cancer-associated EpCAM mutations on protein function." (PMID 37192201, 2023). "Recently, we identified 115 unique cancer-associated somatic/missense mutations in the EpCAM coding region." (PMID 37192201, 2023). "Collectively, our results highlight future therapeutic opportunities in EpCAM and Ras mutated cancers." (PMID 37192201, 2023). "EpCAM-L240A, a cancer- associated EpCAM mutant that is localized in the cytosol, altered normal epithelial cells to a mesenchymal phenotype through ZEB1 and cytokine signaling." (PMID 37192201, 2023). "While metastasis is one of the main causes of cancer treatment failure, the involvement of EpCAM signaling in metastatic processes is unclear." (PMID 37543570, 2023). "During our previous study, we generated several cancer-associated EpCAM mutations to test the effect of cytosolic EpCAM expression on cathepsin-L protease activity." (PMID 37192201, 2023). "Both CD73 and EpCAM overexpression was reported to be implicated in the enhancement of cancer cell proliferation and in resistance towards cytotoxic agents." (PMID 37509310, 2023). "It is well established that EpCAM overexpression is associated with increased cancer cell proliferation." (PMID 37509310, 2023). "EpCAM expression is correlated with tumorigenesis and metastasis in many cancers, so we sought to elucidate the underlying mechanisms in this study." (PMID 37543570, 2023). "We recently catalogued cancer associated EpCAM mutations and identified 115 unique cancer-associated somatic/missense mutations in the EpCAM coding region." (PMID 37192201, 2023). "When mutated, approximately half of all cancer-associated EpCAM mutations localize to the cytosolic compartments, where it cannot inhibit extracellular cathepsin-L." (PMID 37192201, 2023). "To consistently localize EpCAM in the cytosol, we generated a cancer-associated EpCAM mutant (EpCAM-L240A) that is retained in the cytosol compartment." (PMID 37192201, 2023). "It is necessary to understand the cell signaling pathways modulated by EpCAM mutations in different cancer types." (PMID 37192201, 2023). "This suggests that tumors with EpCAM mutations can sensitize cancer cells to unique therapy regimens." (PMID 37192201, 2023).
cancer (continued). "EPCAM encodes a carcinoma-associated antigen, which is being used as a target for immunotherapy treatment." (PMID 36675550, 2023). "Further investigations are needed to assess the role of EpCAM-EVs as diagnostic or prognostic biomarker in cancer." (PMID 36203609, 2022). "Another well known CSC marker is EpCAM expressed by cancers of epithelial origin and its over-expression is associated with poor survival and advanced disease stage." (PMID 35642021, 2022). "In CRC, EpCAM is overexpressed in more than 90% of all cancer cells and is associated with poor prognosis." (PMID 36458008, 2022). "Our data showed a direct correlation between BCG exposure, HLA-I downregulation, EpCAM deficiency, and a shift toward a mesenchymal score in a subset of cancer cells." (PMID 35503263, 2022). "Some researchers didn't rely on initial EpCAM-based capture of CTCs allowing them to identify additional CTC populations being associated with cancer progression." (PMID 35966579, 2022). "Due to the loose adhesion of EpCAM compared to other CAMs, increased expression of EpCAM is associated with invasion, metastasis, and poor prognosis in many cancers, including basal-like and luminal B BCs." (PMID 35986321, 2022). "In this case, DARPins that target the epithelial cell adhesion molecule (EpCAM), a diagnostic cell surface marker for many types of cancer, were employed." (PMID 36232839, 2022). "The expression of EpCAM has been associated with cancer cell proliferation and metastasis, as well as with cancer stem cells." (PMID 35012489, 2022). "In our recent study, we demonstrated that elevated BMP9 expression is associated with poorer HCC prognosis and that BMP9 promotes EpCAM-positive cancer stem cell properties in HCC by inhibiting DNA-binding protein 1 (ID1)." (PMID 35163396, 2022). "Epithelial cellular adhesion molecule (EpCAM) is the most widely used tumor-associated antigen because it is overexpressed in many types of cancer, including breast cancer and colorectal cancer." (PMID 36296024, 2022). "Monoclonal antibody chemotherapy involves the injection of antibodies that locate and disrupt receptors associated with cancer, such as ErbB-2-targeting trastuzumab and EpCAM/CD326-targeting adecatumumab." (PMID 35208277, 2022). "Specifically, in some studies, cancer cells harboring EGFR mutations seemed to have a higher level of EpCAM expression, supporting the strategy of using the current panel to isolate CTC for EGFR mutational testing in our study." (PMID 36142574, 2022). "EPCAM has been considered a prognostic biomarker, as its overexpression has been linked to cancer development, whereas normal levels are hallmarks of normal epithelial cell function." (PMID 36230521, 2022). "Such EMT CTCs, reported in a variety of cancers, are characterised by the loss of epithelial markers (such as EpCAM) and have been known to evade capture by classical EpCAM-based CTC isolation systems." (PMID 34199452, 2021). "EpCAM increased expression in cancer cells compared with normal cells and it is associated with cancer progression and metastasis." (PMID 34790117, 2021). "The high expression of EpCAM was shown to facilitate cancer malignant growth and progression and was associated with poor prognosis and therapeutic irresponsiveness in cancer patients." (PMID 33691694, 2021). "We also studied 13 other cancer-associated EpCAM mutations and discovered that approximately 50% of these mutations prevented EpCAM cell surface expression." (PMID 33980181, 2021). "MOC31PE targets the cancer-associated epithelial cell adhesion molecule, and kills cancer cells by distinct mechanisms, simultaneously causing immune activation by induction of immunogenic cell death (ICD)." (PMID 34019185, 2021). "One example is N-glycosylation of EpCAM, a transmembrane glycoprotein primarily used as an epithelial marker and aberrant expression is associated with cancer." (PMID 34957124, 2021).
cancer (continued). "Studies reveal that somatic mutations in EpCAM are present in up to 5.1% of some tested cancer cohorts, including squamous and melanoma skin cancers." (PMID 33980181, 2021). "Epithelial cell adhesion molecule (EpCAM) is considered to be an important marker of cancer stem cells, and is associated with poor outcomes of HCC." (PMID 34950591, 2021). "Analysis of human cancer sequencing studies reveals that somatic EpCAM mutations are present in up to 5.1% of tested tumors." (PMID 33980181, 2021). "The protein most strongly associated with metformin in our data was EPCAM, a protein that is implicated in cancer pathophysiology and suggested as a circulating cancer biomarker." (PMID 33279861, 2021). "The expression of WDR4 was significantly correlated with mutations in 5 MMR genes (MLH1, MLH2, MLH6, PMS2, EPCAM) in several cancer types." (PMID 34282052, 2021). "EpCAM is a biomarker for cancer stem cells in HCC, and overexpression of EpCAM is associated with poor prognosis in patients with HCC after curative liver resection." (PMID 33675149, 2021). "C66Y is a cancer-associated EpCAM mutation that disrupts an important disulfide bond in the EpCAM TY-1 domain." (PMID 33980181, 2021). "EpCAM (epithelial cell adhesion molecule) is one of the first cancer associated antigens considered as a suitable target for cancer immunotherapy." (PMID 33543415, 2021). "Further research on larger datasets, other ethnicities and other cancer types are warranted for a comprehensive elucidation of the associations of EpCAM -935 C/G polymorphism with cancer risk." (PMID 35070966, 2021). "The findings reported here provide important insights into the biology of this and other cancer-associated EpCAM mutations." (PMID 33980181, 2021). "The monoclonal antibody Catumaxomab, which targets EpCAM and causes an anti-cancer immune response, has been approved for the treatment of malignant ascites in Europe." (PMID 33980181, 2021). "The Catalogue of Somatic Mutations in Cancer (COSMIC) database was queried to tabulate the position and amino acid changes of cancer associated EpCAM mutations." (PMID 33980181, 2021). "EpCAM mutations have also been observed in metastatic lesions and other cancers at a frequency of 1–2%." (PMID 33980181, 2021). "We demonstrate that C66Y and multiple other EpCAM cancer-associated mutations prevent surface expression of EpCAM." (PMID 33980181, 2021). "The high expression levels of EpCAM have been associated with local growth and dissemination in different cancers, including breast and colorectal tumors." (PMID 34354950, 2021). "EpCAM is a tumor-associated antigen that is overexpressed on most epithelial tumors (carcinomas) and therefore suitable for targeted anti-cancer treatment." (PMID 34715784, 2021). "Depending on the dataset and cancer type, EpCAM mutations are present at a frequency between 0 to 5.13% in human cancers." (PMID 33980181, 2021). "More importantly, we demonstrate that EpCAM cancer-associated mutations alter EpCAM cellular function and localization, abrogate the ability of EpCAM to inhibit CTSL activity, and impact CTSL-driven cancer cell invasion." (PMID 33980181, 2021). "EpCAM overexpression in carcinomas is linked to cancer proliferation, migration, and metastasis, and is associated with poor prognosis." (PMID 34055495, 2021). "EpCAM overexpression is often linked to poor prognosis, presumably due to its involvement in cancer cell proliferation, migration, and metastasis." (PMID 32486423, 2020).